F5 (coagulation factor V)
Diseases named in the same sentence as F5 in open-access papers (continued):
Sharing a sentence is not in itself a finding about the gene and the disease.
gastric cancer (5 papers, 2020 to 2025). A primary or metastatic malignant neoplasm involving the stomach. "Here, we show that F5 is highly expressed in gastric cancer tissue and this strongly correlates with advanced TNM stage and shorter OS." (PMID 32190689, 2020). "TCGA data revealed that F5 mRNA levels were significantly upregulated in gastric cancer samples." (PMID 32190689, 2020). "This study reveals that the high expression of F5 in gastric cancer predicts poor survival time." (PMID 32190689, 2020). "Furthermore, the F5 gene is significantly upregulated in gastric cancer tumor tissues and may be a potential prognostic biomarker for gastric cancer." (PMID 33807999, 2021). "Fourthly, as TCGA cohort was unable to obtain the clinical information of postoperative chemotherapy of gastric cancer patients, we could not find the relationship between the expression level of the F5 gene and the prognosis of gastric cancer patients receiving postoperative chemotherapy." (PMID 32190689, 2020). "Among the enriched pathways related to poor prognosis, five theranostic markers of interest were identified as deregulated and enriched in gastric cancer, including vWF, FN1, THBS1, PCDH7, and F5." (PMID 39456895, 2024). "Secondly, the mechanism of F5 regulation in tumourigenesis and the progression of gastric cancer were not further explored." (PMID 32190689, 2020).
hepatocellular carcinoma (5 papers, 2017 to 2025). A malignant tumor that arises from hepatocytes. "These F5-CAFs interact with hepatocellular carcinoma (HCC) cells to promote their proliferation and sustain their stemness." (PMID 40741331, 2025).
lymphoma (5 papers, 2005 to 2025). A malignant (clonal) proliferation of B- lymphocytes or T- lymphocytes which involves the lymph nodes, bone marrow and/or extranodal sites. "Five noninvasive biomarkers (FLT4, SFTPB, GNPTG, F5, and IL-17A) were further validated in an independent lymphoma cohort (n = 39), and another three noninvasive biomarkers (KIT, CCL3, and TNFSF1) were validated in NSCLC cohort (n = 76)." (PMID 38349411, 2024). "To address this question, we validated eight plasma proteins (IL-17A, F5, FLT4, SFTPB, and GNPTG in lymphoma, TNFSF12, CCL3, and KIT in NSCLC) for response prediction and three plasma proteins (IL36G, SERPINC1, and LTA) for relapse monitoring." (PMID 38349411, 2024).
lung carcinoma (4 papers, 2021 to 2023). "We highlight the increased expression of immune-response-related genes FCGBP, BPIFB, F5, CST1, and CFB, and their correlation to epithelial-to-mesenchymal transition (EMT) under SMG, rendering them potential biomarkers of lung cancer progression." (PMID 36613598, 2022). "FCGBP, BPIFB1, F5, CFB, and CST1 and their correlation to EMT key markers displayed a potentially less metastatic phenotype of lung cancer under SMG." (PMID 36613598, 2022). "Overall, these data imply that the differentially expressed FCGBP, F5, CFB, and BPIFB1 in lung cancer may play an important role in lung cancer progression." (PMID 36613598, 2022).
breast tumours (3 papers, 2020 to 2023). "Moreover, high expression of F5 in human breast tumours has been linked to tumour aggressiveness and overall survival." (PMID 37391533, 2023).
pancreatic cancer (3 papers, 2020 to 2025). "We have previously reported on a novel monoclonal antibody (mAb) we designated F5, which was raised against a glycopeptide derived from the tandem repeat (TR) region of Mucin-4 (MUC4), a heavily O-glycosylated protein that is overexpressed in many pancreatic cancer cells." (PMID 40649822, 2025).
arterial disease (2 papers, 2011 to 2021). "This indicated that a tobacco-smoking-related gene (CHRNA3) and a thrombosis-related gene (F5) might play an essential role in PAD but not in other arterial diseases." (PMID 34943774, 2021).
asthma (2 papers, 2022 to 2023). "Such architecture of the network indicates that the revealed key nodes are related to four different compartments of the asthma-associated regulome and some of them (Timp1, F5, Ccl12, Ccl6, Ccl9, Adra2a, and Ear1) can be involved in the regulation of similar processes." (PMID 35625754, 2022).
bacterial sepsis (2 papers, 2017 to 2025). "Some of the hemostasis genes that we identified as candidaemia susceptibility genes (SERPINA1, LAT and F5) have also been shown to be important for bacterial sepsis." (PMID 28727728, 2017).
depression (2 papers, 2022 to 2025). "Finally, we identified ARG1, TPST1 and F5 as core genes associated with S100A12 expression in depression." (PMID 36325528, 2022).
glioma (2 papers, 2015 to 2022). A benign or malignant brain and spinal cord tumor that arises from glial cells (astrocytes, oligodendrocytes, ependymal cells). "In addition, 5 hub genes in hub network 2 were related to the poor prognosis of gliomas, including F5, IGFBP5, TNC, SCG3, and IGFBP3." (PMID 35387222, 2022). "Several genes including e.g. F5, LAMA1, ERBB2 or STARD3 seems to be in proximity to genes of the EGF/EGFR signaling cascade, which is known to be important in glioma." (PMID 25537509, 2015).
Menorrhagia (2 papers, 2021 to 2023). Prolonged and excessive menses at regular intervals in excess of 80 mL or lasting longer than 7 days. "These variants are likely to mediate their effects through increased (VWF) or decreased (F5) blood loss, in women being mainly mediated through menstruation, supported by the finding that factor V Leiden variant protects against menorrhagia." (PMID 33536631, 2021).
prostate carcinoma (2 papers, 2020 to 2021). A carcinoma that arises from epithelial cells of the prostate gland. "Genes such as BUB1B, ANX1A1, F5, HTR4, and MUC4 can be used as biomarkers to assist in the diagnosis and prognosis of prostate cancer." (PMID 34512870, 2021).
anaplastic astrocytoma (1 paper, 2015). "In a dataset of anaplastic astrocytomas, mutations in two of these four genes (PKHD1 and MUC16) were identified and in a set of GBMs, mutations in three genes (MUC16, F5 and PKHD1) were identified." (PMID 26699864, 2015).
Anxiety (1 paper, 2022). Intense feelings of nervousness, tension, or panic often arise in response to interpersonal stresses. "Notably, gastrointestinal vagal deafferentation affected genes previously associated with anxiety modulation in the mouse amygdala (Cldn2, Mfrp, Ttr, F5, Clic6), although in opposite direction compared with acute or early-life stressors." (PMID 35965105, 2022).
Autoimmunity (1 paper, 2022). The occurrence of an immune reaction against the organism's own cells or tissues. "To note, F5 TCR-transgenic mice in a RAG2-deficient background (RAG2-KO) do not develop any intestinal inflammation or autoimmunity." (PMID 35426367, 2022). "In order to rule out any potential extrinsic effects of the inflammatory environment (IBD or autoimmunity) and focus precisely on the specific intrinsic role of SMAD4 in CD8+ T cells, we opted to use naive F5 TCR–transgenic CD8+ T cells, which recognize a peptide from the influenza virus." (PMID 35426367, 2022).
benign adenoma (1 paper, 2023). "In line with the identification of F5, an essential cofactor in blood coagulation, as significantly elevated in metastatic stroma, we have reported its expression to progressively increase from canine mammary normal stroma, benign adenoma and carcinoma." (PMID 37391533, 2023).
Bovine mastitis (1 paper, 2012). INFLAMMATION of the UDDER in cows. "Study in Turkey indicated that genes encoding Shiga toxins 1 and 2 (stx1 and stx2), intimin (eaeA), heat-stable enterotoxin a (Sta), and F5 (K99), F41, and F17 fimbriae were the most prevalent virulence factors which were isolated from clinical bovine mastitis cases." (PMID 23213293, 2012).
colitis (1 paper, 2018). Inflammation of the colon. "A 16-gene signature (CARD12, CCL3, CCR3, CXCL1, F5, FAM210B, GADD45A, IL18bp, IL2RA, IL5, IL8, MMP9, PTGS2, SOCS3, TLR9 and UBE2C) was identified from 30 days post-tremelimumab initiation blood that discriminated patients developing grade 0–1 from grade 2–4 diarrhea/colitis." (PMID 30227886, 2018).
delirium (1 paper, 2023). A disorder characterized by confusion; inattentiveness; disorientation; illusions; hallucinations; agitation; and in some instances autonomic nervous system overactivity. "A CSF proteomic study found that lower preoperative levels of transmembrane domain-containing protein 2B (VSTM2B) and coagulation factor V (FA5) were positively correlated with delirium severity." (PMID 37251808, 2023).
diarrhoea (1 paper, 2025). "Traditionally, strains carrying the F5 (K99) fimbriae have been considered the main cause of E. coli-associated diarrhoea." (PMID 41150125, 2025).
hematoma (1 paper, 2021). A hematoma is a collection of blood from a vascular structure into an extravascular space. "Finally, the factor 5 (F5) hub gene, associated with hematoma and aPHE volumes, is a non-proteolytic co-factor of factor X and an essential part of the prothrombinase complex, and may modulate ICH and aPHE volumes." (PMID 33206327, 2021).
hemorrhage (1 paper, 2018). Loss of blood from the vascular compartment to the exterior or into nonvascular body space as a result of rupture or severance of the blood vessels. "Extracellular serine protease (espP) is responsible for mucosal hemorrhage observed in patients suffering from hemorrhagic colitis, due to cleavage of pepsin A and human coagulation factor V." (PMID 29545780, 2018).
lung adenocarcinoma (1 paper, 2023). A carcinoma that arises from the lung and is characterized by the presence of malignant glandular epithelial cells. "The copy numbers of both the target (CYP2C8, CYP3A4) and the reference genes (ALB, B2M, BCKDHA, F5, CD36, MPO, TBP, RPPH1) established in primary lung adenocarcinoma by the qPCR-based method were congruent with those determined by next-generation sequencing (for 10 genes, slope = 0.9498, r2 = 0.72)." (PMID 37686184, 2023).
mastitis (1 paper, 2023). Inflammation of breast tissue during lactation or postpartum due to an obstructed duct or infection. "The virulence factors, such as adhesion (F5, F41, and Intimin), provide colonization ability to the pathogens in mammary cells as the first step of infection; these genes were the most prevalent virulence factors identified in clinical bovine mastitis cases." (PMID 37235152, 2023).
neuroblastoma (1 paper, 2024). Neuroblastoma (NB) is the most common solid, extracranial childhood tumor. "In this study, we analyzed the inhibitory effects of f5 and f5f3 on extracellular Aβ deposition in SH-SY5Y cells, human neuroblastoma cells, to evaluate the effect on human neurons." (PMID 39682812, 2024).
staphylococcus aureus infection (1 paper, 2022). An infectious process in which the bacteria Staphylococcus aureus is present. "Serpinf2a and f5 were associated with both Staphylococcus aureus infection and complement and coagulation cascades." (PMID 36016944, 2022).
cancer (41 papers, 2012 to 2025). A tumor composed of atypical neoplastic, often pleomorphic cells that invade other tissues. "High F5 gene expression, for instance, may indicate an increased risk of thrombosis, a critical prognostic factor in cancer patients." (PMID 40092689, 2025). "In malignant tumors, its activation is associated with an increased risk of invasion and metastasis, resulting in a worse prognosis; overexpression of F5 in GC could contribute to poor prognosis by promoting cell migration." (PMID 39456895, 2024). "Association of Coagulation factor V (F5) polymorphisms with the occurrence of many types of cancers has been widely reported, but whether it is of prognostic relevance in some cancers remain to be resolved." (PMID 32190689, 2020). "Studies also identify F5 as a D-dimer-related gene, with implications for immune response and cancer survival, suggesting additional regulatory pathways in GC." (PMID 39456895, 2024). "Protein–protein interaction analysis of common DEGs in L. brandtii showed that the most significant core genes were CXCL1, MMP9, JUN, ANXA2, and F5, which regulate immune response and cancer progression." (PMID 32256671, 2020). "This increase in F5 expression, which is crucial for an essential component of the coagulation cascade, implies alterations in coagulation pathways throughout the progression of cancer." (PMID 39456895, 2024). "However, the role and mechanism of F5 gene expression in the prognosis of cancers are still unknown." (PMID 32190689, 2020). "Therefore, we speculate that F5, as a potential oncogene, may affect the prognosis of cancer patients through these biological pathways and overexpression of F5 would lead to poor prognosis in GC." (PMID 32190689, 2020). "Our RNAseq analysis revealed consistent patterns of dysregulation for these biomarkers across all cancer stages, from Stage I to Stage IV, highlighting three of them: fibronectin 1 (FN1), coagulation factor V (F5), and thrombospondin 1 (THBS1)." (PMID 39456895, 2024). "The uniform dysregulation of FN1, F5, and THBS1 across all cancer stages highlights these genes as possible biomarkers and their potential utility in cancer diagnosis and prognosis." (PMID 39456895, 2024).
tumor (26 papers, 2011 to 2025). "Altogether, these findings demonstrate that exercise training reduces the Pf4, Ppbp, and F5 mRNA levels in both the spleen and tumor, and this response is associated with decreased tumor growth in CT26 tumor-bearing mice." (PMID 38081853, 2023). "We sought to determine the ability of F5 to distribute selectively, in vivo, to appropriate tumor tissues, i.e., those that are MUC4+." (PMID 40649822, 2025). "Similar to Pf4, Ppbp, and F5 mRNA expression was increased by more than fivefold in the spleen of CT26 tumor-bearing mice as compared to healthy control mice and exercise training significantly reduced the Ppbp and F5 mRNA levels towards the control levels." (PMID 38081853, 2023). "Consistent with transcriptional changes in the spleen, exercise training also decreased Pf4 and Ppbp, and F5 mRNA levels in the tumor tissue." (PMID 38081853, 2023). "M.R. Asch22 and Cihan Ay23 had revealed tumor was a potential factor for thrombosis, tumor cells can activate the blood coagulation factor V and increase blood viscosity." (PMID 32572092, 2020). "The distribution of F5 gene differed significantly between adjacent tissues and tumour tissues, as well as in different stages as revealed by the scatter diagram." (PMID 32190689, 2020). "Finally, both tumor and spleen Pf4, Ppbp, and F5 mRNA expression were correlated with the CT26 tumor volume." (PMID 38081853, 2023). "Importantly, exercise training was found to reduce Pf4, Ppbp, and F5 mRNA levels in both the spleen and tumor, which was associated with decreased tumor growth in CT26 tumor-bearing mice." (PMID 38081853, 2023). "In conclusion, the current findings show that the F5 gene is upregulated in GC tumour tissues and may be a potential prognostic biomarker for GC." (PMID 32190689, 2020). "However, F5B6 CTLs expressing increased levels of F5 TCR were able to control tumor growth." (PMID 31249570, 2019). "An increased expression of FCGBP, BPIFB, F5, CST1, and CFB and their correlation to epithelial-to-mesenchymal transition (EMT) under clinorotation were detectable as potential tumor suppressor biomarkers." (PMID 37048115, 2023). "Interestingly, we observed increased expression of FCGBP, BPIFB, F5, CST1, and CFB and their correlation to EMT under SMG, rendering them potential tumor suppressor biomarkers." (PMID 36613598, 2022).
infection (10 papers, 2012 to 2026). The state of being infected such as from the introduction of a foreign agent such as serum, vaccine, antigenic substance or organism. "This is supported by the finding of reduced levels of coagulation factor V and decreased factor V activity after experimental infection in dogs." (PMID 39813225, 2025). "The first step in the infection process is the colonization of the intestinal epithelium, which is mediated by ETEC-associated fimbrial adhesins, primarily F5, F17, and F41." (PMID 32819409, 2020). "These cells constitutively express F5, and therefore upon infection with Ad5/40S, fiber mosaic virus particles (displaying both F5 and F40S on their capsids) are formed." (PMID 22860056, 2012).
cardiovascular disease (4 papers, 2007 to 2022). "Our study explores the role in cardiovascular disease of four thrombosis genes: coagulation factor V, intercellular adhesion molecule 1, protein C, and thrombomodulin." (PMID 17677000, 2007). "We investigated the role of four thrombosis genes: coagulation factor V (F5), intercellular adhesion molecule 1 (ICAM1), protein C (PROC), and thrombomodulin (THBD) in cardiovascular diseases." (PMID 17677000, 2007).
myopathy (1 paper, 2015). A disease of the muscle in which the muscle fibers do not function properly. "Birds suffering from this myopathy exhibit down-regulation of eight hemostatic genes (A2M, FGA, FGB, FGG, KNG1, SERPINC1 and VWF) and up-regulation of four other coagulation genes (F5, F10, PROS1 and F2R)." (PMID 26445145, 2015).
F5 also shares sentences with these, for which no sentence is quoted: antiphospholipid syndrome (80 papers); venous thromboembolism (62); hyperhomocysteinemia (61); antithrombin deficiency (38); pulmonary embolism (22); systemic lupus erythematosus (17); preeclampsia (16); protein c deficiency (16); hereditary thrombophilia (15); thromboses (14); myeloproliferative disorder (13); protein S deficiency (12); hemophilia (11); paroxysmal nocturnal hemoglobinuria (10); coronary artery disease (9); protein (9); sickle cell disease (9); Von Willebrand disease (9); atrial fibrillation (8); deficiencies (8); dysfibrinogenemia (7); factor deficiency (6); intrauterine growth restriction (6); myocardial infarction (6); nephrotic syndrome (6); polycythemia vera (6); anemia (5); essential thrombocytemia (5); hematological disease (5); hemophilia A (5).
A further 215 diseases each share a sentence with F5 in 5 papers or fewer.